ACO2 (aconitase 2)
Description:
Catalyzes the isomerization of citrate to isocitrate via cis-aconitate.
Synonyms: ACONM; HEL-S-284; ICRD; OCA8; OPA9
Tractability: PROTAC: ubiquitination databases record sites on it; its protein half-life has been measured.
Gene: Protein-coding gene on chromosome 22 (41,447,830 to 41,529,273, forward strand). Ensembl gene ENSG00000100412.
Subcellular location: Mitochondrion
Subcellular location (Human Protein Atlas): Mitochondria
Pathways (Reactome):
Metabolism: Citric acid cycle (TCA cycle); Maturation of TCA enzymes and regulation of TCA cycle
Metabolism of proteins: Mitochondrial protein degradation
Protein localization: Mitochondrial protein import
Gene Ontology:
Molecular function: iron ion binding; 4 iron, 4 sulfur cluster binding; aconitate hydratase activity
Biological process: citrate metabolic process; tricarboxylic acid cycle; generation of precursor metabolites and energy
Cellular component: mitochondrion; cytosol; mitochondrial matrix
Genetic constraint (gnomAD): Loss-of-function variants: 32 observed, 87.98 expected, observed/expected ratio (o/e) 0.36, 90% interval 0.27 to 0.49. The upper end of that interval is the gene's LOEUF score, 0.49, which puts it in group 2 of 6, group 1 being the genes least tolerant of losing a copy. Missense variants: 683 observed, 1,071.7 expected, observed/expected ratio (o/e) 0.64, 90% interval 0.6 to 0.68. Synonymous variants: 414 observed, 430.74 expected, observed/expected ratio (o/e) 0.96, 90% interval 0.89 to 1.04.
Gene-disease validity (ClinGen):
ClinGen rates the evidence that ACO2 causes each of these diseases.
mitochondrial disease (autosomal recessive): Definitive.
optic atrophy 9 (semidominant): Definitive.
mitochondrial disease (autosomal dominant): Strong.
Homologues: Orthologues: chimpanzee ACO2 (98% identical), guinea pig ACO2 (97% identical), pig ACO2 (97% identical), rabbit ACO2 (97% identical), mouse Aco2 (97% identical), rat Aco2 (96% identical), dog ACO2 (95% identical), macaque ACO2 (95% identical), tropical clawed frog aco2 (89% identical), zebrafish aco2 (83% identical), Caenorhabditis elegans aco-2 (73% identical), Drosophila melanogaster mAcon1 (72% identical), and 1 more. Paralogues in human: ACO1 (30% identical), IREB2 (27% identical).
Diseases named in the same sentence as ACO2 in open-access papers:
ACO2 is named in the same sentence as 86 diseases in open-access papers, as found by Europe PMC text mining. Sharing a sentence is not in itself a finding about the gene and the disease. The quoted sentences say what the papers report.
optic atrophy (12 papers, 2018 to 2025). A disorder characterized by loss of optic nerve fibers. "Fundus changes in patients with variants in seven genes exhibited optic atrophy plus retinal degeneration in our in-house cohort, including ACO2, FDXR, NBAS, OPA3, RTN4IP1, SSBP1 and C12ORF65." (PMID 39423307, 2025). "In conclusion, our study highlights the importance of dominant and recessive ACO2 mutations in patients with isolated or syndromic optic atrophy phenotypes." (PMID 34056600, 2021). "Mutations in the gene encoding citric acid cycle enzyme aconitase 2 (ACO2)/OPA9 were until recently believed to be quite a rare cause of inherited optic atrophy." (PMID 34867178, 2021). "Notably, heterozygous pathogenic ACO2 variants have previously been associated with isolated optic atrophy." (PMID 40210596, 2025). "In European groups of individuals with genetically undecided optic neuropathies, authors recognized more than 60 cases harboring ACO2 variants, 50 of which carried dominant mutations, highlighting the important contribution of pathogenic ACO2 variants to dominant optic atrophy." (PMID 39337438, 2024). "In this study, a homozygous deletion in the ACO2 gene in two brothers with reduced aconitase 2 activity in fibroblasts has been described with symptoms including truncal hypotonia, optic atrophy, hyperopia, astigmatism, and cerebellar atrophy." (PMID 38668366, 2024). "The reported yield of nuclear and mitochondrial DNA sequencing in bilateral optic atrophy is around 20% and includes pathogenic variants in the OPA1, mtDNA genes, or rarely WFS1, MFN2, POLG, ACO2, and DNAJC30 genes." (PMID 36294366, 2022). "In the present study, we identified a heterozygous 51 bp deletion (c.1699_1749del51) in ACO2 in a family with autosomal dominant inherited isolated optic atrophy." (PMID 33028849, 2020). "In the present study, we identified a heterozygous 51 bp in-frame deletion in ACO2 in a family with dominant inherited isolated optic atrophy." (PMID 33028849, 2020). "In humans, ACO2 is expressed ubiquitously and is implicated in ICRD and optic atrophy." (PMID 40210596, 2025). "Biallelic variants in ACO2 are purported to cause two distinct disorders: infantile cerebellar-retinal degeneration (ICRD), characterized by CNS abnormalities, neurodevelopmental phenotypes, optic atrophy, and retinal degeneration." (PMID 36735737, 2023). "Here, we describe pathogenic variants in the ACO2 gene presenting as complex hereditary spastic paraplegia (HSP) with a new phenotype of episodic visual loss after every febrile infection and progressive optic atrophy." (PMID 33500398, 2021). "Some mutations in the mitochondrial aconitase gene (ACO2), similar to IDH3A, can result in severe neurological disease, progressive optic atrophy and retinal degeneration, whilst other mutations in the same gene can give optic atrophy only." (PMID 30478029, 2018).
prostate carcinoma (11 papers, 2016 to 2025). A carcinoma that arises from epithelial cells of the prostate gland. "In summary, here we show that ACO2 is overexpressed in malignant prostate cancer tissues compared with ANT tissues, and its expression is positively correlated with the malignancy of prostate cancer." (PMID 30972978, 2019). "In prostate cancer, cells undergo metabolic transformation from zinc‐accumulating, citrate‐producing cells to citrate‐oxidizing malignant cells with lower zinc levels and higher mitochondrial aconitase (ACO2) activity." (PMID 30972978, 2019). "Our results indicate that ACO2 plays an important role in the development and drug resistance of prostate cancer and suggests that targeting ACO2 may be a useful strategy for prostate cancer treatment." (PMID 30972978, 2019). "Furthermore, ACO2 expression is involved in prostate cancer drug resistance." (PMID 30972978, 2019). "Since intracellular zinc levels are mainly controlled by zinc transporter ZIP1, we then examined the expression profiles of ERRα, ACO2 and ZIP1 in clinical prostate cancer samples using an available prostate cancer dataset." (PMID 40044646, 2025). "In the present study, we have clearly revealed that FABP5 activated expression of metabolic genes (ATP5B, LCHAD, ACO2, FH and MFN2) via a novel signaling pathway in an ERRα (estrogen-related receptor α)-dependent manner in prostate cancer cell lines." (PMID 30167092, 2018). "Collectively, these results indicated that ERRα could directly activate the ACO2 gene, and repress the ZIP1 gene, thus resulting in the dysregulation of zinc homeostasis and citrate metabolism in prostate cancer cells." (PMID 40044646, 2025).
optic neuropathies (8 papers, 2019 to 2025). "Germline ACO2 mutations have been described in optic neuropathy with encephalopathy and cerebellar atrophy, and in infantile cerebellar-retinal degeneration." (PMID 30945144, 2019). "In order to improve diagnostic pathways, we have screened large cohorts of European individuals with molecularly undiagnosed optic neuropathy to determine whether ACO2 variants account for a proportion of cases." (PMID 34056600, 2021). "The closest mammalian ortholog of mAcon1 is aconitase 2 (ACO2), where dominant mutations in ACO2 have been identified in patients with neurodegenerative syndromes, such as optic neuropathies." (PMID 39073591, 2024). "Pathogenic variants of the aconitase 2 gene (ACO2) are responsible for a broad clinical spectrum involving optic nerve degeneration, ranging from isolated optic neuropathy with recessive or dominant inheritance, to complex neurodegenerative syndromes with recessive transmission." (PMID 34354088, 2021). "Interestingly, Aconitase 2 (ACO2), another enzyme of the Krebs cycle that converts citrate into isocitrate, is responsible for both recessive and dominant optic neuropathy, isolated or occurring in syndromic forms with encephalopathy and cerebellar atrophy." (PMID 33806088, 2021). "In addition to these patients with possible inherited optic neuropathies, six other patients (20.0% of patients with an alteration of the GCC) carried suspected unique pathogenic variants in six recessive genes (DPYD, AGXT, CYP1B1, ACO2, LTBP2 and FDXR)." (PMID 38796496, 2024). "The susceptibility variants identified in the other six patients were not firmly responsible on their own for a genetic form of optic neuropathy since they were found in recessives genes (DPYD, ACO2, AGXT, CYP1B1, LTBP2 and FDXR) with a single affected allele." (PMID 38796496, 2024).
Intellectual disability (5 papers, 2017 to 2025). "Approximately 100 patients with aconitase 2 deficiency have been reported with a variety of symptoms, including intellectual disability, hypotonia, optic nerve atrophy, cortical atrophy, cerebellar atrophy, and seizures." (PMID 38668366, 2024). "Taking into account predicted deleterious effects and associations of the affected gene with epilepsy or intellectual disability in these candidate variants revealed two novel compound heterozygous mutations in the gene ACO2 (NM_001098)." (PMID 28463998, 2017). "Mutations in the ACO2 gene were identified in patients suffering from a broad range of symptoms, including optic nerve atrophy, cortical atrophy, cerebellar atrophy, hypotonia, seizures and intellectual disabilities." (PMID 33028849, 2020). "In addition, mutations in the ACO2 gene on chromosome 22q13 were recognized in patients afflicted with a lot of pathological conditions, from progressive cerebellar/cerebral atrophy and optic nerve atrophy to intellectual disabilities and hearing loss." (PMID 39337438, 2024).
mild cognitive impairment (5 papers, 2020 to 2023). "Aco2 activity has previously been studied in the peripheral blood of subjects with Alzheimer’s disease (AD) and mild cognitive impairment (MCI)." (PMID 37240666, 2023). "Similarly, mitochondrial aconitase (ACO2), a Krebs cycle enzyme sensitive to oxidative damage, was found to be reduced in peripheral lymphocytes of AD and mild cognitive impairment subjects and to correlate with antioxidant protection." (PMID 33670490, 2021). "Especially, there were no signs of cerebellar ataxia or cognitive deficits reported before in carriers of biallelic ACO2 mutations." (PMID 33028849, 2020).
breast carcinoma (4 papers, 2020 to 2023). "ACO2-overexpression causes antiproliferation to breast cancer cells, accompanied by a decreasing lactate level, increasing acetyl-CoA level, activating citrate synthase (CS), rising levels of TCA cycle metabolites for citrate, α-ketoglutarate, fumarate, and inducing mitochondrial superoxide." (PMID 35624775, 2022). "Less than 1% of genetic alterations were instead identified for the ACO2 gene in breast cancer according to the TCGA data set." (PMID 31819175, 2020). "Prompted by the evidence that ACO2 levels are downregulated in breast cancer cells and in human breast cancer specimens, we transiently overexpressed myc-tagged ACO2 in MCF-7 cells, demonstrating that high levels of ACO2 reduced cell proliferation." (PMID 31819175, 2020). "Moreover, oxidative stress regulation on the TCA cycle was demonstrated in breast cancer cells and tumor tissues exhibiting low aconitase 2 (ACO2)." (PMID 35624775, 2022). "Although no mutation in ACO2 sequence has been associated with tumour susceptibility, in this paper, we have demonstrated that expression levels of ACO2 are deregulated in breast cancer and that its overexpression in MCF-7 cell line is able to dampen cell proliferation." (PMID 31819175, 2020).
Obesity (4 papers, 2018 to 2023). Accumulation of substantial excess body fat. "A total of 175 genes including thermogenic markers (UCP2, CKMT2, and CITED1) and 5 BATLAS markers (PPARGC1B, ACO2, ACSF2, NNAT, and DMRT2) were expressed less in active beige adipocytes carrying FTO obesity-risk variant as compared to risk-free carriers." (PMID 37416800, 2023). "This network included aconitate hydratase 2 (ACO2), and dihydrolipoyl dehydrogenase (DLD), in which acetylation was significantly increased by obesity." (PMID 30061171, 2018).
retinal degeneration (4 papers, 2018 to 2025). Degeneration of the retina. "In summary, we have successfully established an animal model for ACO2, demonstrating that fly orthologs of human genes linked to cerebellar‐retinal degeneration can replicate relevant disease phenotypes." (PMID 40210596, 2025).
Alzheimer disease (3 papers, 2023 to 2025). A progressive, neurodegenerative disease characterized by loss of function and death of nerve cells in several areas of the brain leading to loss of cognitive function such as memory and language. "Consequently, these two genes were excluded, leaving six critical genes with diagnostic significance for Alzheimer’s disease (AD): ACO2, CS, MRPS27, SDHA, SLC25A20, and SYNJ2BP." (PMID 39757625, 2025).
Ataxia (3 papers, 2019 to 2020). Ataxia refers to impaired coordination of voluntary muscle movement. "In this study, we identified compound heterozygous mutations in ACO2 (p.[Asp512Asn; Gly666Ala]) in a patient with progressive cerebellar and cerebral atrophy, hypotonia, ataxia, seizure disorder, developmental delay, ophthalmological abnormalities and hearing loss." (PMID 31106992, 2019). "We, therefore, supplemented the EOAD- control group with ataxia genotypes that were not reported with comorbid dystonia in literature (including ABHD12; IFRD1; KIAA0226; PHYH; TDP1; VWA3B; GTF2H5; FLVCR1; ACO2; HSD17B4; DNAJC3 gene mutations; PubMed and OMIM)." (PMID 33255407, 2020).
Encephalopathy (3 papers, 2019 to 2025). Encephalopathy is a term that means brain disease, damage, or malfunction. "Interestingly, changes in FGF21-responsive genes such as OXCT1, the SUCL complex, PDHA1, OGDH, ACO2, IDH3B, and ETC components (MT-CO2, COQ9, UQCRQ, SDHB/D and NDUFB7) are linked to mitochondrial deficiency syndromes manifesting cardiomyopathy and encephalopathy." (PMID 40998786, 2025).
Huntington disease (3 papers, 2016 to 2023). Huntington disease (HD) is a rare neurodegenerative disorder of the central nervous system characterized by unwanted choreatic movements, behavioral and psychiatric disturbances and dementia. "For example, Aco2 activity was lower in the blood of Huntington’s disease (HD) patients than in controls." (PMID 37240666, 2023). "Aco2 activity correlated significantly with motor score, independence scale, and functional capacity of the Unified Huntington’s Disease Rating Scale as well as disease duration." (PMID 29160844, 2017). "Finally, we examined if Aco2 activity in PBMC correlates with Unified Huntington’s Disease Rating Scale (UHDRS) in HD patients and PreHD carriers." (PMID 29160844, 2017).
infantile cerebellar-retinal degeneration (3 papers, 2023 to 2024). Infantile cerebellar retinal degeneration (ICRD) is a genetic condition present from birth (congenital) that involves the brain and eyes. "Infantile cerebellar retinal degeneration (ICRD) (OMIM #614559) is a rare autosomal recessive inherited disease associated with mutations in the aconitase 2 (ACO2) gene." (PMID 39600307, 2024). "It has been established that mutations in the ACO2 gene on chromosome 22q13 cause a group of neurodegenerative disorders that include optic atrophy-9 (OPA9) and infantile cerebellar-retinal degeneration (ICRD)." (PMID 39337438, 2024).
iron deficiency (3 papers, 2018 to 2022). "In cellular iron deficiency, IRPs bind to IREs at the 5’ untranslated region (UTR) of FPN1, FtH, FtL, delta-aminolevulinate synthase 1 (ALAS1), aconitase 2 (ACO2), hypoxia-inducible factor 2 (HIF2) mRNAs to mediate the degradation of the transcripts of the IREs to decrease iron storage and export." (PMID 30558109, 2018). "In mammals, ACO2, NDUF8, and SDHB are downregulated in conditions of iron deficiency, but the mechanisms causing this decrease are not the same for all of them." (PMID 35038030, 2022).
asthenozoospermia (2 papers, 2021 to 2023). "In our study, bioinformatics analysis showed that proteins in the PPI network of ACO2, such as SLC25A3, are involved in energy metabolism and differentially expressed in patients with asthenozoospermia." (PMID 34213690, 2021).
cardiac hypertrophy (2 papers, 2014 to 2020). "Fatty acid oxidation (Acadm, Etfdh, Acadl, Acadvl, Eci1, Hadh, Phyh, Acaa2, Hadha, Hadhb, Cd36), glucose metabolism (Dld, Pdha1, Pgam1, Pgam2, Acss1, Ldhb, Fh1, Slc2a4, Aldh6a1), TCA cycle (Aco2, Dld, Fh1, Ogdh, Sucla2, Sdha, Idh3b, Idh2) were up-regulated by hispidulin in cardiac hypertrophy." (PMID 33324687, 2020).
colorectal cancer (2 papers, 2020 to 2023). A primary or metastatic malignant neoplasm that affects the colon or rectum. "The knockdown of ACO2 in colorectal cancer promotes cell proliferation and colorectal cancer growth." (PMID 37601653, 2023).
gastric cancer (2 papers, 2016 to 2019). A primary or metastatic malignant neoplasm involving the stomach. "Decreased expression of aconitase, encoded by ACO1 and ACO2, is described for many types of tumor cells, and represents an unfavorable prognostic marker in gastric cancer." (PMID 30967137, 2019). "ACO2 is another enzyme of the citric acid cycle that is down regulated in stage III/IV gastric cancer." (PMID 27941907, 2016).
glioma (2 papers, 2024 to 2025). A benign or malignant brain and spinal cord tumor that arises from glial cells (astrocytes, oligodendrocytes, ependymal cells). "Immune-related pathways such as TNF signalling (IDH3B/G, MDH1, ACO2, SDHA, OGDHL) and JAK/STAT3 (PIAS2/3, PTPN2, AKT1/2, MCL1, CISH, AOX1) signalling are enriched in gliomas and play a critical role in their progression." (PMID 41007296, 2025).
lung carcinoma (2 papers, 2024 to 2025). "Of these, Aco2, Idh2, Ndufs1, Hadh, Dlat, Itgam, Dlat, Hadha, Mrpl11, Dlst, and Hspd1 show potential as oncoproteins and tumor suppressors and warrant further study for their possible role in inflammation-driven lung cancer." (PMID 40429836, 2025). "A link between reactive oxygen species (ROS) formation by the OXPHOS system and tumor formation has been previously reported in Kras-driven lung cancer models, and we therefore assessed mitochondrial aconitase 2 (ACO2) activity, an established marker for damage induced by high levels of superoxide." (PMID 39485842, 2024).
melanoma (2 papers, 2015 to 2025). A malignant, usually aggressive tumor composed of atypical, neoplastic melanocytes. "By contrast, virtually no double staining of pCREB and either citrate synthase (CS) or aconitase (ACO2), key enzymes in the TCA cycle, was detected in sections from old patients with human primary melanomas." (PMID 41258756, 2025).
optic atrophy 9 (2 papers, 2024). "Optic atrophy 9 (OPA9) is caused by mutations in the aconitase 2 (ACO2) gene, which encodes an enzyme in the mitochondrial matrix." (PMID 39201313, 2024).
Parkinson disease (2 papers, 2023 to 2025). A progressive degenerative disorder of the central nervous system characterized by loss of dopamine producing neurons in the substantia nigra and the presence of Lewy bodies in the substantia nigra and locus coeruleus. "Interestingly, ACO2 deficiency has also been linked to an increased risk of movement disorders, such as Parkinson's disease; however, this association is based on adult data, which may not be directly applicable to paediatric cases." (PMID 40210596, 2025).